ERVV-1 (endogenous retrovirus group V member 1, envelope)
Synonyms: ENVV1; FLJ32214; HERV-V1
Tractability: Antibody: UniProt predicts a signal peptide or a membrane-spanning region. PROTAC: ubiquitination databases record sites on it.
Gene: Protein-coding gene on chromosome 19 (53,013,921 to 53,016,123, forward strand). Ensembl gene ENSG00000269526.
Subcellular location: Membrane
Subcellular location (Human Protein Atlas): Cytosol; Centrosome
Gene Ontology:
Cellular component: membrane
Genetic constraint (gnomAD): Missense variants: 35 observed, 147.97 expected, observed/expected ratio (o/e) 0.24, 90% interval 0.18 to 0.31. Synonymous variants: 14 observed, 47.81 expected, observed/expected ratio (o/e) 0.29, 90% interval 0.19 to 0.46.
Homologues: Orthologues: chimpanzee ERVV-2 (95% identical), chimpanzee ERVV-1 (95% identical), macaque ERVV-1 (91% identical), macaque ERVV-2 (90% identical). Paralogues in human: ERVV-2 (96% identical), ERV3-1 (14% identical), ERVW-1 (12% identical), ERVFRD-1 (10% identical), ERVMER34-1 (10% identical).
Diseases named in the same sentence as ERVV-1 in open-access papers:
ERVV-1 is named in the same sentence as 3 diseases in open-access papers, as found by Europe PMC text mining. Sharing a sentence is not in itself a finding about the gene and the disease.
ERVV-1 shares sentences with these, for which no sentence is quoted: tumor (2 papers); cancer (1); colon carcinoma (1).